HNF1B (HNF1 homeobox B)
Diseases named in the same sentence as HNF1B in open-access papers (continued):
Sharing a sentence is not in itself a finding about the gene and the disease.
infection (4 papers, 2016 to 2025). The state of being infected such as from the introduction of a foreign agent such as serum, vaccine, antigenic substance or organism. "Meanwhile, re-epithelialization, which is defined by the upregulation of epithelial marker genes, was induced at 12 h at the earliest after Ad-HNF1B infection." (PMID 27196561, 2016). "Accordingly, we believe that the expression of HNF-1β target genes should begin to change between 9 h (time of HNF-1β expression) and 12 h (time of re-epithelialization induction) after Ad-HNF1B infection." (PMID 27196561, 2016). "The epithelial marker genes, including γ-GT1, claudin-2, and SLC6A13, were downregulated by TGF-β1 stimulation for 48 h, and then began to increase significantly from 12 h to 18 h after Ad-HNF1B infection." (PMID 27196561, 2016). "These phenotype changes were restored by Ad-HNF1B infection 48 h after TGF-β1 stimulation." (PMID 27196561, 2016). "The downregulated HNF1B gene and HNF-1β recovered to the basal levels at 6 h and 9 h after Ad-HNF1B infection, respectively; furthermore, they had increased remarkably 24 h after infection." (PMID 27196561, 2016). "The HNF-1β was downregulated by TGF-β stimulation for 48 h in the hRPTECs, and its expression began to increase 9 h after infection with Ad-HNF1B." (PMID 27196561, 2016). "Conversely, expression levels of ectodermal (Pax6, Gfap, Neurod1, and Olig1) or mesendoderm (Flk1, Eomes, Hnf1b, and Mixl1) markers either not enhanced or only weakly increased after Cre infection." (PMID 40216251, 2025). "Therefore, to identify the HNF-1β downstream genes that induce re-epithelialization, the genes that were upregulated 9 h after Ad-HNF1B infection were analyzed by DNA microarray (n = 3) and real time RT-PCR." (PMID 27196561, 2016). "If HNF-1β indirectly induces the re-epithelialization mediated through HNF-1β downstream genes, the expression of the downstream gene is thought to change prior to the induction of epithelialization and after the upregulation of HNF-1β following Ad-HNF1B infection." (PMID 27196561, 2016). "However, the expression of Pkd2, Pkhd1, Kif12, Cadherin16 and Socs3, which are known as HNF-1β target genes, did not change (data not shown), and only a few genes, including NR1H4, MITF, SLC3A1, and SLCO4C1, were significantly upregulated 9 h after Ad-HNF1B infection." (PMID 27196561, 2016).
genetic disorder (3 papers, 2024 to 2026). "This is consistent with the fact that individuals with HNF1B mutations do have kidneys, in contrast to certain other human genetic diseases (e.g., FRAS1 or FREM2 mutations) where organogenesis fails to initiate." (PMID 38788724, 2024).
metabolic disease (2 papers, 2023 to 2025). A congenital disorder (due to inherited enzyme abnormality) or acquired (due to failure of a metabolically important organ) disorder resulting from an abnormal metabolic process. "HNF1B is very closely related to so many other metabolic diseases, i.e., it negatively regulates white adipocyte differentiation." (PMID 37511676, 2023). "In general, long-term outcomes of lipid perturbations on metabolic diseases as well as on related morbidity and mortality in patients with HNF4A-MODY, GCK-MODY, HNF1A-MODY, and HNF1B-MODY require future investigations." (PMID 39504571, 2025).
brain) diseases (1 paper, 2024). "Finally, drugs that modulate glutamate signaling are being explored as treatments in non-renal (e.g., brain) diseases, and this suggests that similar drugs may ameliorate features of kidney organogenesis associated with HNF1B mutations." (PMID 38788724, 2024).
endocrine disorders (1 paper, 2021). "Many kidney and endocrine disorders might be explained by pathogenic variants of the HNF1B gene, the major transcription factor encoded in the 17q12.3 region or by deletions on this region." (PMID 35474932, 2021).
gynecologic tumors (1 paper, 2013). "Remarkably, in a cohort of patients having gynecologic tumors with some degree of cytoplasmic clearing, those with HNF1B-positive tumors (by IHC) were significantly more likely (3-fold) to experience a clinically-significant thrombotic event (including DVT, PE and thrombotic stroke)." (PMID 24040285, 2013).
hematological cancers (1 paper, 2022). "In addition to these functions, it has been consistently reported that the HNF1B locus plays a key role in modulating tumorigenesis in solid and hematological cancers, and that its methylation or mRNA expression levels can be used for patient stratification and prediction of disease outcome." (PMID 35625981, 2022).
infectious disease (1 paper, 2024). A disorder directly resulting from the presence and activity of a microbial, viral, or parasitic agent in humans. "It has been documented that all-trans retinoic acid elevates DRA expression in intestinal epithelial cells through HNF-1β, offering therapeutic benefits for diarrhea resulting from intestinal inflammation or infectious diseases." (PMID 39650157, 2024).
HNF1B also shares sentences with these, for which no sentence is quoted: maturity-onset diabetes of the young (18 papers); gout (9); nephronophthisis (8); Bardet-Biedl syndrome (7); Hypocalciuria (6); autosomal recessive polycystic kidney disease (5); epilepsy (5); melanoma (4); Benign Prostate Hyperplasia (3); Dent disease (3); end-stage renal disease (3); Müllerian aplasia (3); neonatal diabetes mellitus (3); osteosarcoma (3); pancreas (3); Polyuria (3); prediabetes (3); renal coloboma syndrome (3); Renal cortical cysts (3); renal dysfunction (3); Renal neoplasm (3); Alagille syndrome (2); Autoimmunity (2); BOR syndrome (2); CHARGE syndrome (2); coronary artery disease (2); Cystic renal dysplasia (2); deafness (2); endocervical adenocarcinoma (2); Esophagogastric Adenocarcinoma (2).
A further 143 diseases each share a sentence with HNF1B in 2 papers or fewer.